AIM2 (absent in melanoma 2)
Diseases named in the same sentence as AIM2 in open-access papers (continued):
Sharing a sentence is not in itself a finding about the gene and the disease.
tumor (continued). "Moreover, a study that involved the mechanism of dihydroartemisinin (DHA) inhibiting tumorigenesis in BC indicated that DHA could induce pyroptosis to suppress tumor progression through promoting the AIM2/caspase-3/DFNA5 axis." (PMID 36276158, 2022). "AIM2, CASP3, NLRC4, TNF, and NLRP6 may be associated with tumour drug resistance." (PMID 35246158, 2022). "Previous study found impaired PINK1 and PRKN expression could promote the degradation of SLC25A37 and SLC25A28 and increase the mitochondrial iron accumulation, which lead to AIM2-mediated HMGB1 release that further induced expression of CD274/PD-L1 in tumor cells." (PMID 36612054, 2022). "Similarly, AIM2 in DCs may play an important role in host immune response and tumor microenvironment." (PMID 34014039, 2021). "Thus, AIM2 in NSCLC exerts tumor‐promoting effects in an inflammasome‐dependent manner and regulation of mitochondrial dynamics, presumably triggering an IL‐1β/STAT3 response by the nuclear factor‐κB (NF‐κB)/COX‐2/HIF‐1α pathway and contributing to the MAPK/ERK pathway activation." (PMID 34014039, 2021). "Furthermore, it has been shown that overexpression of AIM2 could inhibit tumor growth of CRC with BRAF-mutant in vivo." (PMID 33842454, 2021). "AIM2 may have different effects on tumor cells through distinct molecular mechanisms." (PMID 34680930, 2021). "Interestingly, studies have previously reported the tumor-suppressive activity of AIM2 and IFI16." (PMID 32328125, 2020). "In cancers, the role of AIM2 is contentious and it could be either oncogenic or tumor suppressive." (PMID 33291082, 2020). "The six tumor-associated antigens include: absent in melanoma 2 (AIM-2), melanoma-associated antigen 1 (MAGE-1), tyrosinase-related protein 2 (TRP-2), glycoprotein 100 (gp100), epidermal growth factor receptor 2 (HER-2), and interleukin-13 receptor subunit alpha-2 (IL-13Ra2)." (PMID 30150597, 2018). "Therefore, we believed that gene therapy by H1/AIM2 nanoparticles could be an alternative solution to alleviate the tumour growth through enhancing the inflammasome and proinflammatory cytokines." (PMID 30160343, 2018). "Thus it indicated that AIM2 exerted its anti-tumor effect through AIM2 inflammasome formation." (PMID 27167192, 2016). "The results showed elevated levels of AIM2 in tumor tissues, while CASP1, NLRP3, and NLRP1 exhibited low expression in these tumor tissues." (PMID 40026444, 2025). "YY2 overexpression robustly increased the levels of cytosolic DNA, AIM2, ASC, cleaved caspase‐1, and GSDMD‐N, both in cells and in syngeneic graft tumor lesions." (PMID 39903759, 2025). "In support of the anti-tumor activity of AIM2 in CRC, the induction of AIM2 expression in HCT116 CRC cells by lentivirus transfection inhibited cell viability and increased the apoptosis rate." (PMID 40002808, 2025). "P.g. and F.n. upregulate IL-1β mRNA/protein via AIM2 and NLRP3 inflammasome dysregulation in an OSCC cell line, promoting a pro-tumor inflammatory phenotype." (PMID 40924302, 2025). "The AIM2 inflammasome, on the other hand, can either promote or attenuate the EMT process depending on the tumour type." (PMID 41148809, 2025). "Here, we discuss the implications of NLRP3, AIM2 and NLRC4 inflammasomes in both cancer development and tumor suppression as well as the potential for future investigations in this context." (PMID 40692785, 2025). "Overall, AIM2 represents a multifaceted target in CRC, with its anti-tumor effects stemming from its ability to regulate cell signaling, influence the immune microenvironment, and interact with gut microbiota." (PMID 40386782, 2025). "There was a significant inverse correlation between methylation levels of CpG loci and AIM2 gene expression in GBM, with distinct variations observed based on the tumor grade." (PMID 40386782, 2025).
tumor (continued). "Subsequent to this, our discussion centers on the diverse roles of AIM2, IFI16, IFIX, and MNDA, providing a comprehensive elucidation regarding their functions and mechanisms across various tumor types." (PMID 40386782, 2025). "At the AIM2 locus, histone lactylation suppresses ferroptosis via ACSL4 and STAT5B, promoting tumor growth and invasion; inhibition of PKM2 or AIM2 reverses this effect." (PMID 41373440, 2025). "AIM2 expression is frequently dysregulated in NSCLC, with increased levels observed in tumor tissues compared to normal lung tissue reducing overall survival." (PMID 40386782, 2025). "The precise interplay between AIM2 and IL-1β in NPC, particularly how they synergize to inhibit tumor progression, warrants further investigation." (PMID 40386782, 2025). "One cluster termed Triple‐I with the best patient survival showed the highest number of tumor infiltrating lymphocytes along with 22 overexpressed genes, including CXCL9 and AIM2." (PMID 40492347, 2025). "In this context, several data reported the dual role of the inflammasome in BC, in that a pro- and anti-tumor activity of the NLRP3 and AIM2 inflammasomes was, respectively, suggested in this type of tumor." (PMID 40002808, 2025). "For Triple‐I tumors, in addition to IFNG mediated cytotoxic T‐cell tumor killing involving genes, like GZMB, high AIM2 along with NLRP1 expression support a role of pyroptosis via inflammasomes." (PMID 40492347, 2025). "Specifically, according to the authors, TTFields activate the immune system by triggering AIM2-dependent pyroptosis and STING-dependent-type I Interferon (IFN) response, tumor suppression ensuing." (PMID 39857785, 2025). "The findings demonstrated high expression of AIM2 in tumor tissues and low expression of CASP1, NLRP 3, and NLRP1 in tumor tissues." (PMID 40026444, 2025). "Western blot denoted that AIM2 overexpression resulted in an elevation in the expression of LC3B II and Beclin1, and suppressed P62 in tumor tissues." (PMID 39222064, 2024). "have suggested that the expression of AIM2 was markedly decreased in human HCC tissues compared with adjacent normal tissues, AIM2 delayed the tumor progression and correlated with immune cell infiltration." (PMID 38817443, 2024). "Conversely, the knockdown of AIM2 in the LV-D group resulted in increased tumor weight and decreased survival, suggesting that DNASE1L3 enhances the efficacy of the combination therapy via the AIM2 pathway." (PMID 39479454, 2024). "TTField-treated GBM cells induced anti-tumor memory immunity and resulted in 42 to 66% cure rates in a STING and AIM2-dependent manner." (PMID 38195584, 2024). "The recognition of tumor DNA and RNA by STING, AIM2, and TL3, respectively, initiates the recruitment of monocytes to the tumor and metastatic niche, and an antitumoral immune response by T cells." (PMID 39766202, 2024). "AIM2, a member of the IFN-inducible HIN200 protein family, is a cytoplasmic double-stranded DNA sensor and a tumor suppressor." (PMID 38469147, 2024). "Moreover, in mice inoculated with cells overexpressing AIM2, there was a notable delay in tumor growth, an extension in survival rates, increased infiltration of CD11b+ cells compared to control groups, and heightened activation of the inflammasome within the AIM2 overexpressing cells." (PMID 39600708, 2024). "Conversely, AIM2 knockdown decreased CDK1 expression, tumor cell invasion, and metastatic potential, and inhibited the growth and angiogenesis of metastatic tumor cells." (PMID 37497237, 2023). "Meanwhile, As the protein level of AIM2 was highest in Caki-1 among RCC cell lines, the xenograft tumor model and mice tumor metastasis model were constructed using Caki-1 cells with AIM2 knockdown." (PMID 36923928, 2023). "AIM2 is an interferon-inducible protein and contains HIN-200, which can inhibit the cell cycle and hinder tumor growth." (PMID 37497237, 2023).
tumor (continued). "AIM2-/- and caspase 1-/- BMDM, treated with LPS and either dsDNA or tumor CM, similarly produced significantly less IL-1β compared to WT BMDM." (PMID 37449203, 2023). "Considering the lower protein level of AIM2 in ACHN among RCC cell lines, a xenograft tumor model using AIM2 overexpressing ACHN cells in the axilla of nude mice was established." (PMID 36923928, 2023). "Dysregulation of these pathways due to AIM2 overexpression can enhance cell survival, inhibit apoptosis, and promote OSCC cell proliferation, ultimately contributing to tumor growth." (PMID 38067304, 2023). "Most of PRGs displayed higher expression levels in tumor samples compared with normal controls except for AIM2, IL1B, and NLRC4, of which the mRNA expression was decreased in tumor samples." (PMID 37051536, 2023). "AIM2 from TAMs and NLRP3 from DCs elicit anti-tumor immune response indicating the therapeutic potential of specifically delivering correspondence activators." (PMID 36932407, 2023). "Interestingly, FOXO3 and AIM2 showed opposite correlations with macrophages, which may be related to the lack of detailed typing of macrophages (M1 macrophages behaved as tumor suppressors, whereas M2 macrophages behaved as tumor promoters)." (PMID 35847844, 2022). "Thus, the expression of AIM2 in different cells may have different effects on tumor cells." (PMID 35281845, 2022). "The tumor tissues are collected from 4 cases of high-grade and 4 cases of low-grade BLCA patients to ascertain the protein level of AIM2 in BLCA." (PMID 36386141, 2022). "Among these DEGs, 5 genes were down-regulated in tumor group including IL1B, AIM2, IL6, NLRP3, and NLRP6." (PMID 36127654, 2022). "IHC staining validated that the protein levels of AIM2, CASP4, GSDMB, NOD2, and RBCK1 in tumor tissues were much higher than that in adjacent normal tissues." (PMID 36248876, 2022). "In our study, high expression of AIM2 correlates with high survival, and the protein level of AIM2 is significantly higher in low-grade BLCA, suggesting AIM2 is a tumor suppressor." (PMID 36386141, 2022). "For example, AIM2 responds to ionizing radiation-induced DNA breaks in the nucleus and drives the proliferation of IECs, whereas STING senses dying tumor DNA after radiation to exert a protective effect during radiotherapy." (PMID 35954484, 2022). "Similar results were evident in the present study, in which the genetic expression of three genes (AIM2, CASP6, and CASP8) was upregulated in tumor tissues and was validated as protective factors in the multivariate Cox regression analysis." (PMID 35846123, 2022). "Therefore, AIM2 might have different effects in different tumours." (PMID 36163033, 2022). "To explore the correlation between the expression of AIM2 inflammasomes and tumor survival, we performed OS, DSS, and PFI analyses based on the AIM2 inflammasomes score." (PMID 36248785, 2022). "Then, we investigated the expression levels of AIM2, CASP4, GSDMB, NOD2, and RBCK1 in cell lines and tumor tissues by qRT-PCR, IHC." (PMID 36248876, 2022). "The in vitro investigation showed that TTFields-treated tumor cells produced signaling molecules, presumably PICs and T1IFNs, which can induce activation of immune cells in a STING- and/or AIM2-dependent manner." (PMID 35426370, 2022). "On the one hand, both AIM2 overexpression and BCG perfusion alone can lead to tumor cell death and anti-tumor immunity." (PMID 36386141, 2022). "Mice inoculated with AIM2-overexpressed MBT-2 cells show a prolonged survival rate, smaller tumor size, lighter tumor weight, and more infiltration by CD11b+ cells compared to the control." (PMID 36386141, 2022). "Another study found that radiotherapy can activate the AIM2/NLRP3-CasPA-IL-1 signaling pathway in mouse models, promoting tumor elimination." (PMID 35846123, 2022).
tumor (continued). "Our study found that AIM2 overexpression enhances the therapeutic efficacy of BCG immunotherapy in mice, with a more robust infiltration of CD11b+ neutrophils, smaller tumor size and weight, and longer survival time." (PMID 36386141, 2022). "In most tumors, the AIM2 inflammasomes score was significantly and positively correlated with CD8+ T cell abundance in the tumor microenvironment." (PMID 36248785, 2022). "QRT-PCR showed that the expression of AIM2, CASP4, GSDMB, NOD2, and RBCK1 was significantly upregulated in tumor samples." (PMID 36248876, 2022). "AIM2 knockout in cSCC cells led to decreased expression of invasive proteases MMP1 and MMP13, thereby weakening the invasion of tumor cells." (PMID 34104103, 2021). "We determined that knocking down BCL2A1 and AIM2 inhibited PSCC cell proliferation, clone formation, migration in vitro and tumor growth in vivo, supporting their critical role in tumorigenesis." (PMID 33391539, 2021). "Herein, we determined that the expression of AIM2 in GC tissues is lower compared to the adjacent normal tissues, and is further reduced in patients with LNM, late TNM stage and a larger tumor size." (PMID 33859277, 2021). "Interestingly, the DC maturation marker CD83 was significantly more expressed in wt OAd and OAd.TNFa-IL2-treated tumors as well as KO OAd.TNFa.IL2-treated tumors, indicating that virus-induced AIM2-mediated tumor-cell signaling might play a role in DC activation." (PMID 32225009, 2020). "When AIM2-overexpressing OSCC cells were implanted into the tongues of immunodeficient mice, enhanced tumor growth and lymphatic invasion were observed, resulting in a decreased survival rate." (PMID 32903550, 2020). "In summary, this paper shows that OAd.TNFa-IL2 adenovirus virotherapy affects the tumor microenvironment through DAMP and PAMP release and subsequent activation of sensors, such as AIM2." (PMID 32225009, 2020). "We first assessed the immunofluorescence intensity of selected inflammasome components (NLRP1, NLRP3, NLRP6, AIM2, ASC, Caspase-1, IL-1β and IL-18) in tumor cells compared to normal epithelial cells, for each patient." (PMID 33255437, 2020). "Collectively, these studies suggest classical tumor-promotive effects of NLRP3 and AIM2 in epithelial cells." (PMID 32778128, 2020). "Recent progress also indicates that there is an inflammasome-independent role of inflammasome components, particularly AIM2 and ASC, in tumor development." (PMID 28955343, 2017). "It is therefore possible, that reduction in MMP13 and MMP1 production after AIM2 knockdown impairs implantation of cSCC cells in the skin of SCID mice and this way results in delay in tumor growth." (PMID 28526809, 2017). "In sum, these results obtained from the TCGA database indicate that across tumor stages, NLRP1, NLRP3, NLRC3, NLRC4 and AIM2 expression in CRC tissues was significantly less than healthy controls." (PMID 26378020, 2015). "Among the genes analyzed, AIM2 and NLRC3 expression was significantly reduced in stage IV CRC compared to the earlier tumor stages." (PMID 26378020, 2015). "In NPC, NLRP3, AIM2 and RIG-I inflammasomes were overexpressed in the tumour cells and were required for IL-1β production in response to PAMPs and DAMPs in the tumour microenvironment and therapeutic treatment." (PMID 23065753, 2012). "Collectively, these findings indicate that AIM2, RIG-I and NLRP3 inflammasomes in tumour cells are activated by factors from the viral and tumour microenvironments, thus contributing to IL-1β secretion." (PMID 23065753, 2012).
tumor (continued). "Additionally, IFI16 has been shown to suppress the activation of other inflammasomes, such as AIM2 and NLRP3, thereby modulating inflammatory responses in a way that can either promote or inhibit tumor progression depending on the context." (PMID 40386782, 2025). "This study reveals that YY2 high expression‐mediated chromosome missegregation/micronuclei formation triggers pyroptosis and CTL activation by activating AIM2/caspase‐1/GSDMD cytosolic dsDNA response, and YY2/anti‐PD‐L1 combinatorial anti‐tumor therapeutic strategy." (PMID 39903759, 2025). "AIM2 was demonstrated to impede the proliferation and migration of CRC cells through the suppression of the AKT/mTOR signaling pathway and the inhibition of Glil expression, thereby exerting a tumor suppressor effect." (PMID 39744568, 2025). "Consequently, this upregulation of AIM2 led to a suppression of HCC cells proliferation, colony formation, and invasive capabilities, highlighting its tumor-suppressive role." (PMID 40386782, 2025). "The mechanism of action for ICT-107 involves pulsing autologous dendritic cells with peptide epitopes from six antigens—MAGE-1, HER-2, AIM-2, TRP-2, gp100, and IL13Ra2—targeting both tumor cells and cancer stem cells to reduce tumor heterogeneity and limit tumor escape." (PMID 40143152, 2025). "In cells lacking AIM2, Akt activation mediated by DNA-dependent protein kinase (DNA-PK) reduces tumor burden." (PMID 41291696, 2025). "Therefore, blocking AIM2 inflammasome or α1-AR reduces the production of bioactive IL-1β and reverses macrophage phenotype triggered by CAR-T therapy, thus enhancing an anti-tumor effect." (PMID 39857785, 2025). "The role of AIM2 in inflammation and tumor response is not singular; rather, it involves interactions with various molecules, forming a complex regulatory network." (PMID 39744568, 2025). "Our findings may provide a comprehensive understanding of the mechanisms through which AIM2 influences HCC progression and immune responses within the tumor microenvironment." (PMID 39222064, 2024). "Our findings suggest that during HSV-1 infection, AIM2 expression is upregulated in some tumor cell lines (4MOSC1and 4MOSC2) but downregulated in others (SCC7, 4T1, and CT26), while ZBP1 expression is upregulated across all five tumor cell lines tested." (PMID 38693119, 2024). "Notably, in GC mouse models and the tumor epithelium of GC patients, the IL-11-mediated activation of the oncogenic latent transcription factor STAT3 was found to upregulate AIM2 expression." (PMID 39600708, 2024). "Similarly, a novel virus-like particle was effective at inducing cGAS binding, activating STING signaling, and generating type I IFN, and this virus-like particle also induced AIM2 inflammasome formation, GSDMD-mediated pyroptosis, and anti-tumor immunity." (PMID 38195584, 2024). "Consistent with the results from non-tumor samples, all the TIMGs that we identified (ENO1, MUC1, COL5A1, COL11A1, IL11, AIM2, JUNB) as well as FABP7, exhibited significantly or moderately elevated expression in multiple TCGA tumors, including GBM, compared to normal tissues." (PMID 39596296, 2024). "A recent study correlated the presence of the AIM2 inflammasome complex signature with drug sensitivity to the compounds AICAR, AT-7519, bosutinib, DMOG, and Z-LLNLE-CHO, suggesting a potential therapy for these tumour types." (PMID 38168015, 2024). "In tumor tissues, IL-1α, IL-1β, IL1R1, IL1RL1, IL1F10, IL33, CASP1, and AIM2 are highly expressed." (PMID 39461030, 2024). "Of interest, increased cGAS-STING signaling is beneficial in certain pathologies, such as cancer, where AIM2 depletion promotes anti-tumor responses by enhancing STING-dependent type I IFN responses, suggesting specific AIM2 inhibitors are useful but require careful consideration." (PMID 37216118, 2023).